ITLN2 (intelectin 2)
Description:
May play a role in the defense system against pathogens.
Synonyms: HL-2; HL2
Tractability: Antibody: UniProt places it where antibodies can reach, with high confidence; UniProt predicts a signal peptide or a membrane-spanning region; its Gene Ontology location is reachable by antibodies, with medium confidence.
Gene: Protein-coding gene on chromosome 1 (160,944,266 to 160,954,889, reverse strand). Ensembl gene ENSG00000158764.
Subcellular location: Secreted
Gene Ontology:
Molecular function: protein binding; oligosaccharide binding
Cellular component: extracellular region
Genetic constraint (gnomAD): Loss-of-function variants: 27 observed, 33.72 expected, observed/expected ratio (o/e) 0.8, 90% interval 0.59 to 1.1. The upper end of that interval is the gene's LOEUF score, 1.1, which puts it in group 4 of 6, group 1 being the genes least tolerant of losing a copy. Missense variants: 391 observed, 404.19 expected, observed/expected ratio (o/e) 0.97, 90% interval 0.89 to 1.05. Synonymous variants: 148 observed, 149.06 expected, observed/expected ratio (o/e) 0.99, 90% interval 0.87 to 1.14.
Homologues: Orthologues: chimpanzee ITLN2 (98% identical), rabbit ITLN2 (82% identical), macaque ITLN2 (82% identical), zebrafish zgc:153219 (53% identical), zebrafish itln2 (52% identical), zebrafish si:ch211-194p6.8 (52% identical), zebrafish si:ch211-194p6.10 (52% identical), zebrafish itln4 (51% identical), zebrafish itln3 (48% identical), zebrafish itln1 (44% identical). Paralogues in human: ITLN1 (81% identical).
Diseases named in the same sentence as ITLN2 in open-access papers:
ITLN2 is named in the same sentence as 14 diseases in open-access papers, as found by Europe PMC text mining. Sharing a sentence is not in itself a finding about the gene and the disease. The quoted sentences say what the papers report.
asthma (2 papers, 2016 to 2025). "Goblet cell gene expression analysis revealed that HDM exposure induced multiple asthma‐associated transcripts, including chloride channel calcium‐activated 1 (Clca1/Gob‐5), mucin 5, subtypes A and C, tracheobronchial/gastric (Muc5ac), intelectin 1 (Itln1), and intelectin 2 (Itln2/B)." (PMID 27621809, 2016). "The large SVs also contained genes related to immune response, such as LY9, ITLN2, and CHIA, which may be linked to asthma susceptibility in the JH pig." (PMID 40372724, 2025). "The ITLN2 and CHIA genes have been reported to link to asthma susceptibility in humans." (PMID 40372724, 2025).
parasite infection (2 papers, 2022 to 2025). "Mouse intelectin(s) 1-6 have been detected in other tissues (e.g., Itln6 is constitutively expressed in colon), and some may be inducible (i.e., Itln2 during parasitic infection)." (PMID 36072603, 2022). "In addition, a previous study in mice showed that ITLN2 may play a role in the innate immune response to parasite infection, as ITLN2, one of the most abundant proteins expressed in infected jejunal epithelium, was upregulated in response to infection by GI nematodes." (PMID 40076885, 2025).
COVID-19 (1 paper, 2022). A disease caused by infection with severe acute respiratory syndrome coronavirus 2. "As seen in G2, interlectin 2 (ITLN2) was found to be downregulated in a study of 22 blood samples of severe COVID-19 patients as well." (PMID 35438176, 2022).
diarrhoea (1 paper, 2022). "Other DEGs that were down-regulated in the high-diarrhoea group include Ovar-DRB1, DQA, TREM2, TFF3, ITLN2, CD74, CCL5, and CCR3." (PMID 35140270, 2022).
latent infections (1 paper, 2021). "In particular, detection of latent infections in animals with focal lesions, which may be sometimes difficult to detect when the animal has low numbers or sparsely distributed granulomas, yet these animals would show numerous ITLN2 labelled cells." (PMID 34065919, 2021).
lung carcinoma (1 paper, 2021). "While none of the adipokines showed any specific trend, ITLN1 and/or ITLN2 genes encoding human omentin were consistently and significantly downregulated in lung cancers." (PMID 33450975, 2021).
nematode infection (1 paper, 2018). "Hence, the expression of genes such as ITLN2, CLCA1, galectin 14, etc. appear to be consistently affected by nematode infection, in both lambs and adult sheep." (PMID 29703268, 2018).
pneumonitis (1 paper, 2022). An inflammatory process affecting the lung parenchyma. "Several of these filtered candidates were found to be secreted (C12orf49, COL10A1, FNDC4, ITLN2, MATN3, PDZD2, RS1, SCRG1, and ST6GALNAC5) making them potential candidate biomarkers useful for distinguishing IPF from pneumonitis." (PMID 35628257, 2022).
infection (10 papers, 2011 to 2025). The state of being infected such as from the introduction of a foreign agent such as serum, vaccine, antigenic substance or organism. "The most prominent genes which were exceedingly up-regulated in the intestine tissue at 4 hour post infection with E. granulosus encode intelectin 2 (ITLN2) and lysozyme C2, responsible for the first line of host defense against parasite." (PMID 26252489, 2015). "In cattle, ITLN2 was identified as a marker for paratuberculosis and plays an important role in the innate immune response to infections." (PMID 40076885, 2025). "This study analyzes the potential use of ITLN2, a protein that has been described as fundamental in the innate immune response to infections, as a biomarker of MAP infection." (PMID 34065919, 2021). "This increased expression of ITLN2 at early stages of infection has been observed in various species, including channel catfish, amphioxus and mouse." (PMID 34065919, 2021). "Previous studies have shown that the intelectin 2 plays an important role in expel intestine parasite infection, and the lysozyme participates in host defense against bacterial infection." (PMID 26252489, 2015). "ITLN2 expression increases upon infection with MAP compared to control samples." (PMID 31619718, 2019). "Before infection, the non-carriers had significantly (P < 0.05) elevated levels of ITLN-2, TFF2, and Ovar-Gal14 compared to the carriers." (PMID 21385411, 2011).
cancer (1 paper, 2022). A tumor composed of atypical neoplastic, often pleomorphic cells that invade other tissues. "Studies analyzing the relationship between ITLN and cancer are focused on ITLN1; the available literature on ITLN2 and cancer is limited." (PMID 35186726, 2022). "We recently identified ITLN1 and ITLN2 mRNA as increased in the visceral adipose tissue of gastrointestinal cancer patients and found that local but not circulating ITLN1 protein demonstrated a relationship with cancer cachexia." (PMID 35186726, 2022).
ITLN2 also shares sentences with these, for which no sentence is quoted: bacterial infection (2 papers); epithelioid mesotheliomas (1); Pleural effusion (1); tumor (1).